AHR (aryl hydrocarbon receptor)
Diseases named in the same sentence as AHR in open-access papers (continued):
Sharing a sentence is not in itself a finding about the gene and the disease.
adenoma (4 papers, 2017 to 2023). A neoplasm arising from the epithelium. "So, we generated tumor organoids using single cells derived from the adenomas of ApcMin/+ and ApcMin/+ AhR -/- mice." (PMID 37781044, 2023). "Pathological examination revealed that even the larger AhR+/+ tumors were pre-malignant adenomas whereas a significant fraction of those present in AhR−/− mice progressed to malignant hepatocarcinomas." (PMID 28874739, 2017). "Liver carcinogenesis induced by diethylnitrosamine (DEN) produced large carcinomas in all AhR−/− mice but mostly premalignant adenomas in less than half of AhR+/+ mice." (PMID 28874739, 2017). "Similarly, we found that the ApcMin/+ AhR -/- mice showed a lower incidence of adenoma in both the small and large intestines when compared with the ApcMin/+ controls." (PMID 37781044, 2023). "Jaffrain-Rea in 2009 reported that the AHR and its partner AIP were downregulated in aggressive somatotropinomas as compared to non-invasive adenomas suggesting their involvement in the acquisition of an aggressive phenotype." (PMID 33281746, 2020). "A comparison of AhR+/+ and AhR−/− mice in the combined carcinogen-inflammation (AOM/DSS) model showed that significantly higher levels of overall tumor incidence, the number of adenomas per mouse, tumor volume and the number of adenocarcinomas per mouse were observed in the AhR knockout mice." (PMID 38651159, 2023). "Interestingly, OCT4 and NANOG expression did not significantly differ between AhR+/+ adenomas and AhR−/− carcinomas, a result that probably reflects a differential function of both genes in regeneration after acute toxicity with respect to liver carcinogenesis." (PMID 28874739, 2017).
Airway obstruction (4 papers, 2021 to 2025). Obstruction of conducting airways of the lung. "This activates aryl hydrocarbon receptor signaling, resulting in increased mucus production, impaired mucociliary clearance, airway obstruction, and respiratory distress." (PMID 37376070, 2023).
autism spectrum disorder (4 papers, 2021 to 2025). A spectrum of developmental disorders that includes autism, and Asperger syndrome. "In neurodevelopmental disorders such as autism spectrum disorder (ASD), where neurotransmitter dysregulation is prevalent, targeting the tryptamine pathway and AHR signalling could present new treatment opportunities." (PMID 39812050, 2025). "Moreover, it can be hypothesized that the interaction of AHR with oestrogen receptors and the presence of MAO on the X chromosome contribute to the sex differences observed in autism spectrum disorder." (PMID 39812050, 2025).
Burkitt lymphoma (4 papers, 2008 to 2023). A rare form of malignant mature B-cell non-Hodgkin lymphoma. "To ascertain that DNA methylation was affected by Iso-3, consistently with inhibition of DNMT1 activity, we investigated expression levels of the aryl hydrocarbon receptor (AHR) gene in Burkitt's lymphoma RAJI cells." (PMID 27006469, 2016). "Here, we report for the first time promoter hypermethylation as a mechanism for AHR repression in a Burkitt's lymphoma model." (PMID 27006469, 2016).
enteritis (4 papers, 2021 to 2024). Inflammation of the small intestine. "In studies using an enteritis model, a decrease in indole-3-acetic acid, an AhR agonist, induces intestinal inflammation via decreased IL-22 production, suggesting that AhR has anti-inflammatory properties." (PMID 38191517, 2024). "For example, AHR expression in ILC3s is reduced in inflamed intestinal tissue, AHR−/− mice typically exhibit mild spontaneous enteritis, DSS-induced enteritis is more severe in AHR−/− mice than in wild-type mice, and AHR−/− mice are more susceptible to Citrobacter infection." (PMID 36432480, 2022). "IDO can alleviate DSS-induced enteritis by regulating tryptophan metabolites KYN and KYNA in MSCs, activating transcription factor aryl hydrocarbon receptor (AhR), and upregulating the expression of TNF-stimulated gene 6 (TSG-6)." (PMID 33859701, 2021).
food allergy (4 papers, 2016 to 2025). Gastrointestinal disturbances, skin eruptions, or shock due to allergic reactions to allergens in food. "Furthermore, the administration of baicalein up-regulated AhR expression in mLNs isolated from food allergy model mice." (PMID 27561877, 2016). "We have previously shown that activation of the ligand-dependent transcription factor aryl hydrocarbon receptor (AhR) by the environmental pollutant 2,3,7,8-tetrachlorodibenzo-p-dioxin (TCDD) affects both oral tolerance and food allergy." (PMID 28666018, 2017). "Thus, the action of baicalein as an agonist of AhR can induce Treg differentiation and enhance barrier function, suggesting that baicalein might serve as an effective immune regulator derived from foods for the treatment of food allergy." (PMID 27561877, 2016). "Furthermore, we confirmed that the enhancement of intestinal barrier function by baicalein was not related to AhR expression and activation in the epithelium from the food allergy mouse model." (PMID 27561877, 2016).
HCMV infection (4 papers, 2021 to 2024). "propose that Hypoxia-inducible factor 1α plays a significant role in the antiviral response by inhibiting the synthesis of Kyn and activating AhR during HCMV infection." (PMID 38680494, 2024). "In recent years, some scholars have verified that HCMV infection can activate AHR by upregulating Kyn and activating AHR requires viral gene expression." (PMID 36829212, 2023). "The identification of KYN allowed us to define a mechanistic connection between HIF1α, IDO1, and AhR during HCMV infection." (PMID 33758082, 2021). "Follow up studies are needed to establish the molecular mechanisms by which endogenous AHR signaling modulates HCMV infection." (PMID 33746961, 2021). "Additionally, HCMV infection regulates the activation of AhR, which in turn modulates the transcription of infected cells." (PMID 38680494, 2024). "Hence, it can be inferred that the activation of AhR by Kyn during HCMV infection serves as a mediator for essential functions in the interaction between the virus and the host." (PMID 38680494, 2024). "We find that blocking AhR signaling reduced HCMV replication, suggesting that HIF1α imparts an antiviral effect by decreasing KYN synthesis and AhR activation in HCMV infection." (PMID 33758082, 2021).
Huntington disease (4 papers, 2021 to 2023). Huntington disease (HD) is a rare neurodegenerative disorder of the central nervous system characterized by unwanted choreatic movements, behavioral and psychiatric disturbances and dementia. "In Huntington’s disease (HD), the absence of AhR improves the behavioral and neurological phenotype." (PMID 34685709, 2021).
intestinal tumor (4 papers, 2018 to 2024). "This multifaceted function establishes AhR as a crucial regulator in host responses to infections, autoimmune disorders, and intestinal tumor development." (PMID 39767818, 2024). "Indeed, in comparison to APCMin/+ mice that spontaneously developed intestinal tumours, APCMin/+/AhR+/− mice exhibited increased tumour incidence, suggesting a tumour suppressor role for AhR." (PMID 32487227, 2020). "Since colon stem cells are precursors of intestinal tumors, we used an inducible deletion of the AhR in an Leucine-rich-containing G-protein coupled receptor 5 (LGR5) expressing model and examined the role of the AhR in colonic stem and progenitor cells." (PMID 38651159, 2023). "For example, ablation of AHR accelerates intestinal tumor formation by stabilizing β-catenin by mechanisms that do not involve AHR's transcriptional activity." (PMID 30254109, 2018). "Our studies investigated the role of the AhR in colon tumorigenesis using wild-type and AhR-knockout mice, the inflammation model of colon tumorigenesis using mice treated with azoxymethane (AOM)/dextran sodium sulfate (DSS) and APCS580/+; KrasG12D/+ mice all of which form intestinal tumors." (PMID 38651159, 2023).
irritable bowel syndrome (4 papers, 2022 to 2025). Irritable bowel syndrome (IBS) is a chronic functional condition of the lower gastrointestinal (GI) tract characterized by abdominal pain or discomfort and disordered bowel habit (diarrhea, constipation, or fluctuation between the two). "The AhR/IL-22 pathway is anticipated to be a new target for addressing symptoms linked to post-infectious irritable bowel syndrome." (PMID 41019044, 2025). "Kurarinone (KAR) has a therapeutic role in irritable bowel syndrome (IBS) by modulating macrophage functions via stimulating AHR signaling." (PMID 37179416, 2023).
lung squamous cell carcinoma (4 papers, 2019 to 2023). "For example, an AhR high-signature is associated with an unfavorable prognosis, whereas an AhR low-associated signature is associated with a favorable prognosis in lung squamous-cell carcinoma (LUSC)." (PMID 33451095, 2021).
metastatic melanoma (4 papers, 2020 to 2023). A melanoma that has spread from its primary site to another anatomic site. "We showed that sustained activation of AhR induces the expression of genes associated with resistance to BRAF inhibitors in the treatment of metastatic melanoma." (PMID 33451095, 2021). "Among the flavonoids tested, Api was the most powerful to counteract BRAFi resistance in metastatic melanoma by antagonizing AhR activity." (PMID 32708687, 2020).
microcephaly (4 papers, 2020 to 2025). A congenital or acquired developmental disorder in which the circumference of the head is smaller than normal for the person's age and sex. "Interestingly, a recent study demonstrated that activation of AHR by its endogenous ligand kynurenine was a fundamental link in microcephaly caused by Zika virus." (PMID 33260776, 2020).
migraine (4 papers, 2020 to 2025). "KP products are important ligands to the aryl hydrocarbon receptor (AhR), whose activation is implicated in the pathogenesis of GI and migraine." (PMID 34576297, 2021). "Based on the data reported in the current study, we propose the possibility to repurpose (off-target use) formerly anti-migraine Avitriptan for local intestinal use as anti-IBD treatment through the AhR." (PMID 32316498, 2020). "The aim of this review is to justify the view that KP modulation may provide common triggers for migraine and FGIDs with the involvement of TLR, AhR, and MyD88 activation." (PMID 34576297, 2021).
myocarditis (4 papers, 2018 to 2025). Myocarditis is a condition that is characterized by inflammation of the heart muscle (myocardium). "In myocarditis, the involvement of AhR is mainly due to its participation in immune system functioning." (PMID 39000041, 2024). "In 2016, it was first reported that AhR modulated the development of myocarditis during Trypanosoma cruzi infection." (PMID 29984241, 2018). "There is strong evidence to suggest that AhR is a pivotal molecule in myocarditis." (PMID 29984241, 2018).
osteoarthritis (4 papers, 2019 to 2025). A noninflammatory degenerative joint disease occurring chiefly in older persons, characterized by degeneration of the articular cartilage, hypertrophy of bone at the margins and changes in the synovial membrane. "In contrast, an increased AhR expression was detected in synovial tissue of patients with RA compared to osteoarthritis patients, indicating that AhR is associated with the pathophysiology of RA." (PMID 34944003, 2021). "In a previous study, the anti-inflammatory effect of IPA was confirmed in osteoarthritis via the AhR/nuclear factor kappa-B (NF-κB) axis." (PMID 40745657, 2025).
osteosarcoma (4 papers, 2017 to 2025). A usually aggressive malignant bone-forming mesenchymal neoplasm, predominantly affecting adolescents and young adults. "On the other hand, AHR activation by TCDD in human osteosarcoma cells is associated with an increased aggressiveness, leading to a higher expression level of receptor activator of NF-kB ligand (RANKL)." (PMID 35465323, 2022). "This has been observed in osteosarcoma cell lines, where elevated CYP1B1 mRNA and protein levels result from AhR pathway activation." (PMID 41155673, 2025). "We also observed downregulation of transcription factors AHR (Aryl Hydrocarbon Receptor), FOSB (FBJ Murine Osteosarcoma Viral Oncogene), and KLF4 (Kruppel-Like Factor)." (PMID 29123522, 2017).
postmenopausal osteoporosis (4 papers, 2024 to 2026). Metabolic disorder associated with fractures of the femoral neck, vertebrae, and distal forearm. "Taken together, these findings identified IA as a promising therapeutic candidate capable of suppressing osteoclastogenesis through an AhR-dependent mechanism, providing mechanistic insight and a potential strategy for the treatment of postmenopausal osteoporosis." (PMID 41522356, 2026). "In this study, supplementation with Trp metabolites, indole acetic acid (IAA), and indole‐3‐propionic acid (IPA), markedly ameliorate bone loss by repairing intestinal barrier integrity in ovariectomy (OVX)‐induced postmenopausal osteoporosis mice in an AhR‐dependent manner." (PMID 39041942, 2024).
renal failure (4 papers, 2020 to 2024). "To isolate the role of AHR activation from the complex milieu of renal insufficiency, we generated a mutant AHR that displays constitutive transcriptional activity in the absence of ligands (termed CAAHR herein)." (PMID 38652558, 2024). "AhR−/− females survived and developed a less severe renal insufficiency that WT mice, reflected by urea, creatinine, and IS measurement in serum." (PMID 32260098, 2020). "In the adenine diet-induced CKD model, we demonstrated that renal insufficiency severity was reduced in AhR−/− mice compared to WT mice." (PMID 32260098, 2020). "The levels of urea, creatinine, and indoxyl sulfate (IS) in the serum of adenine-fed mice showed that WT and AhR−/− exhibited renal insufficiency." (PMID 32260098, 2020). "However, surviving AhR−/− males had moderate renal insufficiency compared to the WT mice, and the renal insufficiency of AhR−/− females was even lower." (PMID 32260098, 2020). "WT females and males presented a renal insufficiency mimicking human CKD, as determined by the dosage of serum urea, creatinine, IS, and AhR-AP." (PMID 32260098, 2020). "Taken together, our results suggest that low expression of XDH, CYP2E1, and SULT1A1, combined with the absence of renal AhR, may explain the low level of renal insufficiency observed in AhR−/− mice in the adenine-induced CKD model." (PMID 32260098, 2020).
retinal degeneration (4 papers, 2016 to 2025). Degeneration of the retina. "Being an agonist of AHR, I3C treatment shows inhibition of retinal degeneration through suppressing microglial activity, inflammation, and oxidative stress via modulation of AHR." (PMID 40094833, 2025). "Novel indole containing AhR activators and their down-stream lipid modulators can be important novel targets for a number of retinal degenerations including AMD." (PMID 27364765, 2016). "The observed anti-inflammatory and neuroprotective effects suggest that AhR may be a potential therapeutic target for retinal degeneration." (PMID 33143743, 2020). "To our knowledge, we here show for the first time that AhR also regulates microglia homeostasis in the degenerating retina and that its natural ligand I3C protects from acute light damage, a model system that mimics certain aspects of human retinal degeneration." (PMID 33143743, 2020). "Finally, we show that, as a downstream effector of 2AI-mediated AhR activation, palmitoleic acid protects RPE cells from 4HNE-mediated stress, and light mediated retinal degeneration in mice." (PMID 27364765, 2016).
Salmonella Infections (4 papers, 2023 to 2025). Infections with bacteria of the genus SALMONELLA. "The AhR molecule is involved in the cooperative influence of VD3 and butyrate on the integrity of the intestinal barrier against Salmonella infection." (PMID 38680494, 2024). "Salmonella infection induced VDR and AhR mRNA expression in the cecal tissue of mice and, the combination of PP and VD3 synergistically enhanced both mRNA expression." (PMID 36672703, 2023). "AhR and VDR proteins were present at significantly increased levels in cecal mucosa in Salmonella colitis through the treatment of PP and VD3, compared with the Salmonella infection only." (PMID 36672703, 2023). "Hence, we researched the participation of AhR-regulated tight junction functions on the united effects of butyrate and VD3 on intestinal defense to Salmonella infection." (PMID 36678175, 2023).
skin aging (4 papers, 2019 to 2025). The gradual irreversible changes in structure of skin that occur as a result of the passage of time.. "They interact with a variety of nuclear receptors, including the vitamin D receptor, aryl hydrocarbon receptor, liver X receptors, and the retinoic acid-related orphan receptors α and γ, through which skin aging can be prevented, mitigated, or treated." (PMID 37513428, 2023). "Hexane-soluble tobacco smoke extract may induce matrix metalloproteinase-1 expression in human skin fibroblasts through the activation of the aryl hydrocarbon receptor pathway, which is pathogenetically involved in extrinsic skin aging." (PMID 40735362, 2025). "Although pigmentary changes and wrinkles are commonly attributed to ultraviolet exposure, experimental and epidemiologic evidence suggests that long-term PM2.5 exposure may contribute to extrinsic skin aging through oxidative, inflammatory, and aryl hydrocarbon receptor-mediated pathways." (PMID 41598216, 2025). "Hence, we conclude that the development of transient AHR antagonists that are suitable for topical application in humans and their in-depth characterization in preclinical models are important in terms of prevention and treatment of environmentally induced skin aging and skin carcinogenesis." (PMID 31795255, 2019). "Whether AHR-driven alterations of the plasminogen activation system are of functional relevance for extrinsic skin aging has not been investigated so far." (PMID 31795255, 2019).
systemic sclerosis (4 papers, 2020 to 2024). A chronic disorder, possibly autoimmune, marked by excessive production of collagen which results in hardening and thickening of body tissues. "We propose that the timely administration of small-molecule AHR agonists may have therapeutic effects on inflammatory diseases, including gut/cutaneous/lung GVHD, IBD, and systemic sclerosis." (PMID 37394584, 2023).
T-cell leukemia (4 papers, 2012 to 2023). A malignant disease of the T-lymphocytes in the bone marrow, thymus, and/or blood. "The aryl hydrocarbon receptor (AhR) pathway is also implicated in leukemogenesis, where, for example, primary human T-cell leukemia cells have shown up-regulated AhR expression and activation." (PMID 22754483, 2012). "We found that the aryl hydrocarbon receptor (AHR) was a tunable knob and controlled HTLV-1 latency-reactivation switching, and the activation of Notch1 signaling by HTLV-1 Tax promoted proliferation of adult T cell leukemia cells." (PMID 34572904, 2021).
thyroid tumor (4 papers, 2005 to 2021). A benign or malignant neoplasm affecting the thyroid gland. "For example, thyroid hormone disruption by ETU causes thyroid tumors; some PBBs act through the aryl hydrocarbon receptor, whereas other PBBs are phenobarbital-like pleiotrophic inducers of liver enzymes and liver tumors." (PMID 16140616, 2005). "In addition, cellular models of PTC are used to systematically analyze the expression levels of other components of the AHR signaling pathway, and to better elucidate the molecular link between BRAFV600E and AHR in thyroid tumor." (PMID 26392334, 2015).
uremia (4 papers, 2014 to 2024). A clinical syndrome associated with the retention of renal waste products or uremic toxins in the blood. "Deletion of the AHR disrupts uremia-induced mitochondrial OXPHOS dysfunction in skeletal muscle." (PMID 38652558, 2024). "Another strategy that might be employed to reduce uremia could be modulation of the AhR-signaling pathway since the uremic toxin IS is also a potent activator of AhR." (PMID 24823865, 2014).